USP7 (ubiquitin specific peptidase 7)
Diseases named in the same sentence as USP7 in open-access papers (continued):
Sharing a sentence is not in itself a finding about the gene and the disease.
non-small cell lung carcinoma (22 papers, 2015 to 2025). A group of at least three distinct histological types of lung cancer, including non-small cell squamous cell carcinoma, adenocarcinoma, and large cell carcinoma. "For example, in lung cancer, overexpression of USP7 is directly associated with non-small-cell lung cancer (NSCLC) cell glycolysis and survival." (PMID 40061891, 2025). "For instance, USP7 promotes non-small cell lung cancer progression by deubiquitinating and stabilizing KRAS." (PMID 41488674, 2025). "For instance, USP7 (ubiquitin-specific protease 7) promotes non-small-cell lung cancer (NSCLC) cell metabolism by activating c-Abl and HK2." (PMID 41330897, 2025). "This study elucidates the profound impact of the USP7 inhibitor GNE-6776 on non-small cell lung cancer (NSCLC), showcasing its potential as a multi-mechanistic therapeutic agent." (PMID 40006058, 2025). "USP7 has also been found to promote glycolysis and cell survival in non-small cell lung cancer by stabilizing and activating c-Abl." (PMID 40389405, 2025). "Mechanistic analyses revealed two functional targets of FTO; first, upregulation of Myeloid Zinc Finger Protein 1 (MZF1) in lung squamous cell carcinoma (LUSC), and second: ubiquitin-specific protease-7 (USP7) in non-small cell lung cancer (NSCLC)." (PMID 35409166, 2022). "Consistent with this assessment, one study also showed a correlation between low USP7 expression levels and poor patient prognosis in non-small cell lung cancer." (PMID 36291159, 2022). "USP7 expression was correlated with poor outcome of several cancers, such as non small cell lung cancer, large cell carcinoma, and lung squamous cell carcinoma." (PMID 34812471, 2021). "Of note, USP7 is highly expressed in non-small cell lung cancer (NSCLC) and correlated with poor overall survival of patients, excluding adenocarcinoma." (PMID 32300595, 2020). "USP7 promotes the proliferation of non-small cell lung cancer cell via stabilizing Ki-67 protein." (PMID 34812471, 2021). "In non-small cell lung cancer (NSCLC), USP7 was recently reported to deubiquitinate and stabilize estrogen receptor β (ERβ), and USP7-promoted ERβ stabilization is potentiated by ROS-induced stimulation." (PMID 39406703, 2024). "In non-small cell lung cancer (NSCLC) studies, possibly due to a different genetic background, USP7 is considered to be a tumor suppressor." (PMID 34556124, 2021). "In non-small cell lung cancer, suppression of PRDX3 induced by a ubiquitin specific peptidase-7 (USP7)-mediated manner could mitigate intracellular ROS and promote Osimertinib resistance." (PMID 41049446, 2025). "In non-small cell lung cancer, FTO has been demonstrated to enhance tumor proliferation through multiple m6A-dependent mechanisms, including activation of KRAS signaling and upregulation of USP7 and MZF1." (PMID 39773744, 2025).
glioma (20 papers, 2013 to 2025). A benign or malignant brain and spinal cord tumor that arises from glial cells (astrocytes, oligodendrocytes, ependymal cells). "Recent studies have highlighted the positive association between USP7 expression and PD-L1 protein levels in gliomas and gastric cancer." (PMID 38474186, 2024). "Because USP7 is associated with patient prognosis and disease progression in gliomas, we first focused on the expression of USP7 in GBM tissue samples." (PMID 34556124, 2021). "Although the association of MGMT with glioma prognosis is well-established, our results indicate that USP7 may serve as both a GBM prognostic marker and a therapeutic target, potentially functioning in association with MGMT, as suggested by our TMA IF data." (PMID 40835840, 2025). "In gliomas, USP7 is consistently overexpressed and intricately linked to PD-L1 expression." (PMID 38474186, 2024). "USP7 expression was significantly lower in low-grade gliomas (grade II) compared with high-grade gliomas (grades III and IV) (p < 0.01)." (PMID 40835840, 2025). "A tissue microarray (TMA) of 92 glioma specimens was used to assess the clinical significance of the USP7-MGMT axis." (PMID 40835840, 2025). "Knocking down USP7 in glioma cells reduced their growth, increased apoptosis, and enhanced CD8+ T cell proliferation, thereby preventing immune evasion." (PMID 38638430, 2024). "The overexpression of PD-L1 counteracted the effects of USP7 silencing on the immune escape of glioma cells." (PMID 38638430, 2024). "In gliomas, expression of USP7 is positively correlated with disease progression and poor patient survival." (PMID 34556124, 2021). "The suppression of USP7 in glioma cells hampers their growth and induces apoptosis." (PMID 38474186, 2024). "Knocking down USP7 in glioma cells enhanced CD8+ T cell proliferation, prevented immune evasion." (PMID 38638430, 2024). "USP7 stabilizes PD-L1 by deubiquitination and contributes to the immune evasion of glioma cells." (PMID 38474186, 2024). "A tissue microarray was used to measure the expression of KPNB1 and USP7 in glioma tissues." (PMID 38254206, 2024). "In glioma cells, USP7 showed high expression levels, but PD-L1 protein levels increased." (PMID 38638430, 2024). "USP1 in glioma, as well as USP7 and USP34, also converge on EZH2 to promote tumorigenesiss." (PMID 37892185, 2023). "One recent investigation observed the overexpression of USP7 and PD-L1 proteins in glioma." (PMID 37415977, 2023). "USP7, UBE2G2, and BTRC were associated with better prognosis of glioma(HR<1, P<0.001)." (PMID 35774799, 2022). "Abrogated USP7 expression promotes CD8+ T cell proliferation, elevates tumor necrosis factor (TNF) alpha and interferon gamma (IFN-γ) levels, and inhibits glioma cell immune evasion, which can be reversed by PD-L1 overexpression." (PMID 37415977, 2023). "The prognostic significance of USP7 and MGMT in gliomas was assessed using the PrognoScan database." (PMID 40835840, 2025). "Additionally, a separate study has also established a correlation between USP1, USP7, and USP22 with glioma stemness due to their ability to enhance the protein stability of inhibitor of DNA binding 1 and Lysine (K)-specific demethylase 1A respectively." (PMID 40034124, 2025). "We performed immunofluorescence (IF) staining on a glioma tissue microarray (TMA) comprising 92 glioma samples and adjacent non-tumor tissues to assess the correlation between USP7 and MGMT expression." (PMID 40835840, 2025). "Additionally, we used a GBM tissue microarray to verify the positive correlation between USP7 and KPNB1 expression in gliomas." (PMID 38254206, 2024). "Furthermore, USP7 inhibits LSD1 ubiquitination and stabilizes LSD1in glioma." (PMID 30150556, 2018).
glioma (continued). "While linked to several DNA repair pathways, USP7 and USP24 expression was not significantly different among glioma groups or between glioma and the non-tumor control group in the Sun dataset, suggesting that these two DUBs may not be critical factors in DNA damage repair pathways in glioma." (PMID 37892185, 2023).
melanoma (19 papers, 2019 to 2026). A malignant, usually aggressive tumor composed of atypical, neoplastic melanocytes. "Several USPs, such as USP4 and USP7, have been implicated in promoting melanoma development, highlighting the essential roles of ubiquitination regulators in this disease." (PMID 40788071, 2025). "We proved that USP7 levels are higher in melanoma than that of normal skin and are associated with poorer prognosis based on analysis from TCGA datasets." (PMID 33869052, 2021). "Taken together, our results suggest that loss of USP7 function inhibits the melanoma cell cycle and promotes cell apoptosis by mediating AMPK and PI3K/Akt/FOXO signaling pathway activity." (PMID 33869052, 2021). "We confirmed that USP7 was highly expressed in clinical melanoma tissues and its loss of function significantly inhibited proliferation of melanoma cells and promoted apoptosis." (PMID 33869052, 2021). "The decreased expression levels of TIP60 or USP7 were associated with melanoma progression, which suggested these two proteins play an important role in modulating the levels of ac-DNMT1 in melanoma metastasis." (PMID 34572918, 2021). "Moreover, depletion or pharmacological inhibition of USP7 dampens cell migration and invasion and increases melanoma susceptibility to BRAF inhibitors." (PMID 39135915, 2024). "Accordingly, USP7 loss inhibits melanoma growth by partially activating the AMPK signaling pathway." (PMID 33869052, 2021). "Altogether, these proteins were confirmed in both melanoma cell lines after USP7 loss, which indicated that USP7 may control the signaling pathways involving in these proteins to promote melanoma development and progression." (PMID 33869052, 2021). "Treatment of these cells with different doses of the chemotherapy drugs (BRAF inhibitor), dabrafenib or vemurafenib, used in melanoma treatment revealed that USP7- or EZH2-deficient cells were more sensitive to chemotherapeutics, which could be partially rescued by FOXO1 knockdown." (PMID 33849069, 2021). "Here, using an integrated chemical biology approach, we explore cellular functions of the DUB USP7 as a case study by comparing inhibition and degradation in melanoma and pancreatic cancer cells." (PMID 42129197, 2026). "In BRAF-mutant MM27 PDX xenografts, the combination of domatinostat with the USP7 inhibitor P5091 was well-tolerated and inhibited melanoma growth accompanied by apoptosis induction and reduction of senescent cell numbers in the tumors." (PMID 39935431, 2025). "Senescence in PDX BRAF-mutant MM27 melanoma cells was inhibited by deubiquitinase (DUB) USP7-mediated stabilization of RRM2." (PMID 39935431, 2025). "Previous studies have reported that USP7 promoted the progression of hepatoblastoma, and melanoma through the PI3K/AKT signaling pathway." (PMID 40384855, 2025). "Our group has also demonstrated that USP7 inhibition suppresses melanoma cell proliferation, migration, and invasion." (PMID 39135915, 2024). "In tumor progression, consistent findings show that USP7 levels are increased in both the transition from nevi and benign to cutaneous melanoma and also in melanoma tissue relative to normal tissue." (PMID 35884430, 2022). "USP7 depletion or pharmacological inhibition by P22077 treatment in melanoma or murine (B16) cell lines has been shown to alter tumor expansion in vivo, cell proliferation in vitro, and migration and invasion." (PMID 35884430, 2022). "Of clinical translational relevance, patients with high ac-DNMT1 protein levels, or high-acDNMT1 with concurrent low DNMT1, high TIP60, or high USP7 protein levels showed significantly better prognosis for 4-year melanoma-specific survival." (PMID 34572918, 2021).
melanoma (continued). "In this study, mass spectrometry-based deep proteomic analysis was carried out following USP7 knockdown to explore the mechanism of action of USP7 in regulating melanoma growth." (PMID 33869052, 2021). "Though we found an oncogenic role of USP7 with melanoma, nonetheless, the substrate requirement for USP7 to promote the progression in melanoma required further exploration." (PMID 34469054, 2021). "These events were shown to be due to the downregulation of TIP60/USP7 protein expression in advanced stage melanoma metastasis." (PMID 34572918, 2021). "We performed TMT-based quantitative proteomic analysis to evaluate the A375 human melanoma cells treated with siRNA of USP7." (PMID 33869052, 2021). "Next, we analysed the USP7 expression in melanoma from TCGA data programmed online tool GEPIA and found that tumours with higher USP7 expression correlated with poor overall survival in melanoma." (PMID 34469054, 2021). "To clarify the mechanism of action of USP7 in melanoma, we compared whole-cell proteomes in WT and USP7 knockdown A375 cells using TMT quantitative proteomics technology." (PMID 33869052, 2021). "The results showed that USP7 expression was negatively correlated with overall survival of melanoma patients in the TCGA dataset (P < 0.05)." (PMID 33869052, 2021). "Our results revealed that USP7 acts as an oncogene in melanoma through mediating PI3K/AKT/FOXO as well as AMPK signaling pathways, and through some new pathways, such as peroxisome and lysosome signaling pathways." (PMID 33869052, 2021). "In this study, we mainly focused on the PI3K-Akt, FOXO, and AMPK signaling pathways to clarify the roles of USP7 in melanoma." (PMID 33869052, 2021). "KEGG analysis of the proteomic data and western blot results reveal that the AMPK signaling pathway plays a role in USP7 mediating melanoma growth." (PMID 33869052, 2021). "ATP6V0C and PEX11B, proteins regulated by USP7, were confirmed in both melanoma cell lines by western blot." (PMID 33869052, 2021). "In summary, these findings reveal an important role of USP7 in regulating melanoma progression via PI3K/Akt/FOXO and AMPK signaling pathways and implicate USP7 as an attractive anticancer target for melanoma." (PMID 33869052, 2021). "Altogether, these results demonstrate that USP7 expression is upregulated in melanoma and is correlated with patients’ poor outcomes." (PMID 34469054, 2021). "The USP7 expression significantly upregulated in 77.5% of all melanomas (31/40), whereas USP7 expression was significantly downregulated in non‐malignant melanocytes." (PMID 34469054, 2021). "In this study, we found that a notable number of melanoma patients contain high USP7 expression, which correlates with reduced overall survival." (PMID 34469054, 2021). "To explore USP7 expression levels relative to melanoma development and progression, we built USP7 knockdown A375 cells by shRNA or siRNA and USP7 KO B16 cells." (PMID 33869052, 2021). "One of these, E3 ubiquitin ligase RNF169 is deubiquitylated and stabilized by USP7 in response to DNA double-strand breaks, and is significantly decreased in the USP7 knockdown, which suggests USP7 in melanoma also plays a role in DNA repair." (PMID 33869052, 2021). "To explore the relationship between USP7 and malignancy of melanoma, first, we examined the expression level of USP7 in a human tissue microarray comprising 40 melanoma specimens from 40 patients (23 female and 17 male, age: 15–80; mean 55)." (PMID 34469054, 2021). "Colony formation assays showed that USP7 or EZH2 depletion hampered the colony formation of melanoma A375 cells, which was also rescued, to some extent, by knockdown of FOXO1." (PMID 33849069, 2021).
melanoma (continued). "Collectively, these results demonstrate that USP7 is overexpressed in human melanoma and predicts clinical outcomes." (PMID 33869052, 2021). "Recently, the elevated USP7 expression was reported as a distinct gene signature of malignant melanoma." (PMID 33849069, 2021). "Therefore, USP7 plays a role at several scales in melanoma by monitoring the mitogenic activation of the PI3K-AKT signaling pathway, metabolic activation by controlling the redox status of cells, and epigenetic and transcriptional regulation." (PMID 35884430, 2022). "Importantly, Kaplan–Meier survival analysis from The Cancer Genome Atlas (TCGA) datasets showed that either a high expression level or increased copy number of USP7 correlated with poor survival in melanoma patients." (PMID 33849069, 2021). "Besides, compared with the normal epithelial cells, the USP7 protein level was also higher in melanoma cell lines." (PMID 34469054, 2021). "We also obtained similar results in melanoma cells following USP7 knockdown." (PMID 33869052, 2021). "We found that a high expression of USP7 in melanoma patients correlated with poor overall survival." (PMID 34469054, 2021). "Here, we found that USP7 is overexpressed in human melanoma by tissue microarray." (PMID 33869052, 2021). "Collectively, this study demonstrated USP7 as a possible oncogenic molecule for melanoma progression, and inhibition of USP7 might be a potential strategy for the suppression of melanoma growth." (PMID 34469054, 2021). "In summary, these data suggest that USP7 is a tumor promoter and can serve as a therapeutic target for melanoma, potentially as a novel therapeutic strategy to respond to the resistance of advanced melanoma to chemotherapy." (PMID 33869052, 2021). "Our data suggest that targeting USP7 would provide a potential strategy for melanoma treatment." (PMID 34469054, 2021). "Moreover, analysis of the integrated cancer microarray database Oncomine indicated that USP7 mRNA levels are strikingly increased in benign melanocytic skin nevus and melanoma samples." (PMID 33849069, 2021). "The IHC staining and the quantitation analysis revealed that compared to the normal skin tissue, USP7 and EZH2 were highly expressed but FOXO1 was expressed at a lower level in melanoma samples, and the expression levels of USP7 with EZH2 or FOXO1 were correlated with cancer progression." (PMID 33849069, 2021). "Together, these findings are consistent with a role for USP7 in promoting melanoma." (PMID 33849069, 2021). "We found that the phosphatidylinositol-3-kinases/Akt (PI3K-Akt), forkhead box O (FOXO), and AMP-activated protein kinase (AMPK) signaling pathways may be closely related to USP7 expression in melanoma." (PMID 33869052, 2021). "However, the expression and role of USP7 in melanoma remains to be elucidated." (PMID 33869052, 2021). "Consequently, we conclude that USP7 plays a role in melanoma through AMPK signaling." (PMID 33869052, 2021). "Furthermore, proteomic data analysis and western blot results showed the importance of the classical signaling pathways PI3K/Akt/FOXO and AMPK, and that new biological processes involve proteins such as ATP6V0C, CASP7, and PEX11B, which play crucial roles in USP7 mediating melanoma growth." (PMID 33869052, 2021). "However, the functional role of USP7 in melanoma remains elusive." (PMID 33869052, 2021). "al revealed that targeting the USP7/RRM2 axis drives senescence and sensitizes melanoma cells to HDAC/LSD1 inhibitors." (PMID 38635758, 2024). "Next, we analyzed the expression profiles of USP7, EZH2 and FOXO1 in human samples from histologically normal skin tissues in tumor-adjacent regions, nevus, malignant melanoma and metastatic melanoma." (PMID 33849069, 2021). "We therefore examined the USP7 protein levels to understand the relationship between DNMT1 and ac-DNMT1 as related to TIP60 and melanoma progression." (PMID 34572918, 2021).